TMCO1 (transmembrane and coiled-coil domains 1)
Description:
Endoplasmic reticulum (ER) calcium-selective channel preventing intracellular Ca2(+) stores from overfilling and maintaining calcium homeostasis in the ER. In response to endoplasmic reticulum (ER) Ca2(+) overloading, assembles into a homotetramer, forming a functional calcium-selective channel facilitating Ca2(+) release. Mediates ER Ca2(+) homeostasis in osteoblasts and plays a key role in bone formation, via the CaMKII-HDAC4-RUNX2 signaling axis (By similarity). Component of the multi-pass translocon (MPT) complex that mediates insertion of multi-pass membrane proteins into the lipid bilayer of membranes. The MPT complex takes over after the SEC61 complex: following membrane insertion of the first few transmembrane segments of proteins by the SEC61 complex, the MPT complex occludes the lateral gate of the SEC61 complex to promote insertion of subsequent transmembrane regions. Within the MPT complex, the GEL subcomplex may mediate insertion of transmembrane regions into the membrane.
Synonyms: TMCC4; PNAS-136; HP10122; CFSMR1; PCIA3
Tractability: Antibody: UniProt predicts a signal peptide or a membrane-spanning region. PROTAC: ubiquitination databases record sites on it; its protein half-life has been measured.
Gene: Protein-coding gene on chromosome 1 (165,724,293 to 165,827,755, reverse strand). Ensembl gene ENSG00000143183.
Subcellular location: Endoplasmic reticulum membrane; Golgi apparatus membrane; Mitochondrion membrane
Subcellular location (Human Protein Atlas): Endoplasmic reticulum
Gene Ontology:
Molecular function: calcium channel activity; protein binding; ribosome binding
Biological process: calcium ion transmembrane transport; endoplasmic reticulum calcium ion homeostasis; ER overload response; multi-pass transmembrane protein insertion into ER membrane; ossification
Cellular component: endoplasmic reticulum; endoplasmic reticulum membrane; Golgi membrane; multi-pass translocon complex; mitochondrial membrane; membrane
Genetic constraint (gnomAD): Loss-of-function variants: 19 observed, 19.86 expected, observed/expected ratio (o/e) 0.96, 90% interval 0.67 to 1.4. The upper end of that interval is the gene's LOEUF score, 1.4, which puts it in group 5 of 6, group 1 being the genes least tolerant of losing a copy. Missense variants: 143 observed, 195.71 expected, observed/expected ratio (o/e) 0.73, 90% interval 0.64 to 0.84. Synonymous variants: 69 observed, 69.45 expected, observed/expected ratio (o/e) 0.99, 90% interval 0.82 to 1.21.
Homologues: Orthologues: chimpanzee TMCO1 (100% identical), dog TMCO1 (100% identical), guinea pig TMCO1 (100% identical), macaque TMCO1 (100% identical), mouse Tmco1 (100% identical), rat Tmco1 (100% identical), zebrafish tmco1 (95% identical), rabbit TMCO1 (88% identical), pig TMCO1 (86% identical), tropical clawed frog tmco1 (85% identical), Drosophila melanogaster CG10470 (73% identical), Caenorhabditis elegans F22B5.10 (61% identical).
Diseases named in the same sentence as TMCO1 in open-access papers:
TMCO1 is named in the same sentence as 29 diseases in open-access papers, as found by Europe PMC text mining. Sharing a sentence is not in itself a finding about the gene and the disease. The quoted sentences say what the papers report.
glaucoma (18 papers, 2012 to 2025). Increased pressure in the eyeball due to obstruction of the outflow of aqueous humor. "Meanwhile, a large number of genetic association studies have revealed that specific single-nucleotide polymorphisms (SNPs) in the TMCO1 gene are significantly associated with the risk of developing primary open-angle glaucoma (POAG)." (PMID 40867644, 2025). "In humans, TMCO1 has been linked to glaucoma, and loss of either TMCO1 or CCDC47 causes rare autosomal recessive developmental disorders." (PMID 32820719, 2020). "TMCO1 has been linked to glaucoma, and mutations in it cause cerebrofaciothoracic dysplasia, a human disease characterized by severe intellectual disability, distinctive facial features, and bone abnormalities." (PMID 32820719, 2020). "TMCO1 dysfunction in humans is associated with dysmorphism, mental retardation, glaucoma and the occurrence of cancer." (PMID 30962442, 2019). "We investigated the associations of the GAS7 rs11656696 minor allele (A) and the TMCO1 rs7555523 minor allele (C) with glaucoma in 4 case-control studies from the Netherlands and Germany." (PMID 22570627, 2012). "Additionally, both Kaplan–Meier analysis and the Cox proportional hazards model indicate that the TMCO1 genotype is clinically significant for assessing glaucoma risk." (PMID 40867644, 2025). "Variants in TMCO1 can cause craniofacial and skeletal anomalies and glaucoma." (PMID 39651291, 2024). "Interestingly, it has also been shown that TMCO1 functionally interacts with other glaucoma-associated genes including CAV1." (PMID 32545285, 2020). "TMCO1 is also known to be associated with severe glaucoma risk." (PMID 29496776, 2018). "The second variant that we found to be associated with IOP and glaucoma was rs7555523 in TMCO1, a highly evolutionary conserved gene of largely unknown function." (PMID 22570627, 2012). "GAS7 and TMCO1 are expressed in ocular cells and tissues implicated in glaucoma." (PMID 22570627, 2012). "Studies from different laboratories have revealed that the mutation or deficiency of TMCO1 is closely correlated with several diseases, including cerebro-facio-thoracic dysplasia (CFTD), glaucoma, premature ovarian failure (POF), osteoporosis, and cancer." (PMID 40867644, 2025). "Among genes implicated in glaucoma, either by GWAS or as rare Mendelian alleles, most were expressed predominantly within RGCs (e.g., OPTN, TMCO1, TBK1)." (PMID 32555229, 2020). "We identified common variants in GAS7 and TMCO1 that altered the susceptibility to both IOP and glaucoma." (PMID 22570627, 2012). "GAS7 and TMCO1 are expressed in the ocular tissues that are involved in glaucoma." (PMID 22570627, 2012). "Individuals homozygous for the rs4656461 TMCO1 risk allele have been found to develop glaucoma 4–5 years earlier than non-carriers in families with a strong family history; however, none of the reported TMCO1-associated risk alleles are located in coding regions of the TMCO1 gene." (PMID 34093650, 2021). "TMCO1 has recently been associated with severe glaucomatous visual field loss, indicating that this locus may influence both the normal variance in IOP and the risk of developing severe glaucoma." (PMID 22570627, 2012). "Both TMCO1 and CDKN2B-AS1 contributed to severe forms of glaucoma." (PMID 30405695, 2018).
glioma (4 papers, 2023 to 2025). A benign or malignant brain and spinal cord tumor that arises from glial cells (astrocytes, oligodendrocytes, ependymal cells). "Furthermore, in glioma cell lines and ovarian granulosa cells, TMCO1 knockdown is associated with decreased levels of BCL-2, potentially affecting the BH3 profile and therefore sensitivity to BCL-2 inhibitors used in our study." (PMID 39353922, 2024). "They found that TMCO1 knockout can induce apoptosis and inhibit cell proliferation in U87 and U251 cells, thereby suppressing glioma malignancy and prolonging survival in glioma patients." (PMID 40867644, 2025). "In glioma research, the upregulation of TMCO1 has been shown to facilitate epithelial-mesenchymal transition (EMT) in U87 and U251 cell lines, thereby enhancing cell migration and invasion." (PMID 39479348, 2024). "In the context of cancer, TMCO1 expression appears to be cancer-specific, with higher expression in gliomas, lung, colon and ovarian cancers and a downregulation in urothelial cancers." (PMID 39353922, 2024). "Another study found that the ER transmembrane protein transmembrane and coiled-coil domains 1 (TMCO1) is important for maintaining calcium homeostasis, promoting EMT in human gliomas, and inducing cell migration and invasion." (PMID 36890838, 2023).
cerebrofaciothoracic dysplasia (3 papers, 2021 to 2025). "Twenty seven patients, from diverse ethnic groups, have been reported with pathogenic TMCO1 variants now recognized to cause cerebrofaciothoracic dysplasia (CFTD)." (PMID 34093650, 2021).
primary open angle glaucoma (3 papers, 2012 to 2025). "We investigated whether polymorphism rs7555523 (A > C) in human transmembrane and coiled-coil domain 1 (TMCO1) gene is a risk factor for primary open angle glaucoma (POAG) in a Saudi cohort." (PMID 27687253, 2016).
breast carcinoma (2 papers, 2024 to 2025). "Given the prognostic relevance of breast cancer molecular subtypes, we further explored the association between TMCO1 expression with subtypes and found elevated TMCO1 expression in all subtypes." (PMID 39353922, 2024). "In summary, we identified that TMCO1 gene and protein expression is increased in all breast cancer subtypes and higher TMCO1 expression is associated with poorer survival in more advanced basal breast cancers." (PMID 39353922, 2024). "Collectively, these results show that the endoplasmic reticulum Ca2+ leak channel TMCO1 is a regulator of apoptosis in basal breast cancer cell lines induced by agents previously linked to endoplasmic reticulum Ca2+ levels." (PMID 39353922, 2024). "TMCO1 expression had a modest association with relapse-free survival of all breast cancer patients overall and in node-positive breast cancer patients." (PMID 39353922, 2024). "We assessed if TMCO1 gene copy number and expression was associated with any specific breast cancer molecular subtype." (PMID 39353922, 2024). "Future studies assessing the transcriptome profile of basal breast cancer patients with high versus low TMCO1 expression could provide a gene signature associated with TMCO1 overexpression, and new insights into the possible contribution of TMCO1 to basal breast cancer metastasis." (PMID 39353922, 2024). "To validate this phenomenon, we assessed the ability of TMCO1 silencing to promote apoptosis to MCL-1 inhibition in another invasive basal breast cancer cell line, HCC1806." (PMID 39353922, 2024). "This along with extensive work linking regulators of endoplasmic reticulum Ca2+ homeostasis and cell death, highlighted the importance of considering TMCO1 in the regulation of cell death pathways in basal breast cancer cells." (PMID 39353922, 2024). "Our finding that TMCO1 silencing only promoted apoptosis to agents to which the breast cancer cells are already sensitive to suggests a likely role for TMCO1 in regulating stress tolerance responses in breast cancer cells." (PMID 39353922, 2024). "In this study, we explored the role of the endoplasmic reticulum Ca2+ leak channel TMCO1 in breast cancer." (PMID 39353922, 2024). "In this study, we link the overexpression of TMCO1 with prognosis in node-positive basal breast cancer patients." (PMID 39353922, 2024). "Basal breast cancers had a modest but significantly lower level of TMCO1 mRNA than Luminal A and Luminal B in both data sets, but there was no strong association between TMCO1 mRNA levels and breast cancer molecular subtype." (PMID 39353922, 2024). "Consistent with previous reports, we found higher TMCO1 expression in breast cancer compared to normal breast tissues." (PMID 39353922, 2024). "To define the role of TMCO1 in Ca2+ homeostasis in the highly metastatic MDA-MB-231 basal breast cancer cells, we assessed the consequences of TMCO1 silencing on Ca2+ signals associated with endoplasmic reticulum Ca2+ stores." (PMID 39353922, 2024). "Given the link between the TGFβ pathway and breast cancer invasion and metastasis, we explored the possible role of TMCO1 in TGFβ-mediated nuclear transport." (PMID 39353922, 2024). "To further explore the ability of TMCO1 silencing to promote death in basal breast cancer cells, we performed cell death studies using other basal breast cancer cell lines that have been previously assessed in the context of Bcl-2 inhibition." (PMID 39353922, 2024). "To gain insights into the function of TMCO1 in basal breast cancer cells we performed proteomic analyses." (PMID 39353922, 2024). "We also characterised the role of TMCO1 in the regulation of endoplasmic reticulum Ca2+ signals in a basal breast cancer cell line." (PMID 39353922, 2024). "As such, we explored the functional role of TMCO1 using basal breast cancer cell lines in the studies below." (PMID 39353922, 2024).
breast carcinoma (continued). "However, higher TMCO1 expression was significantly correlated with poorer survival in node-positive basal breast cancer patients." (PMID 39353922, 2024). "TMCO1 mRNA expression was positively correlated with gene copy number (Spearman’s correlation R-value = 0.6395), suggesting that the increased TMCO1 expression in breast cancers is the result of gene copy number alterations." (PMID 39353922, 2024). "Although there has been increasing interest in the possible roles of TMCO1 in various cell types, in contrast to IP3Rs, little is known about the function, expression pattern and interacting partners of TMCO1, particularly in breast cancer cells." (PMID 39353922, 2024). "Approximately 70% of TCGA breast cancer patients had a gain in at least one copy of the TMCO1 gene." (PMID 39353922, 2024). "Due to the recency of TMCO1’s association with endoplasmic reticulum Ca2+ regulation and a lack of studies in breast cancer, we sought to evaluate the expression, interacting proteins and consequences of TMCO1 inhibition on Ca2+ signalling and cell death in breast cancer cells." (PMID 39353922, 2024). "Finally, we assessed whether TMCO1 expression was correlated with breast cancer patient relapse-free survival using a log-rank test." (PMID 39353922, 2024). "Indeed, TMCO1 protein was significantly elevated in the luminal A, luminal B and basal breast cancer subtypes compared to normal breast, indicating that elevated TMCO1 may be a general feature of breast cancers." (PMID 39353922, 2024). "Interacting proteins included nuclear transport proteins and TMCO1 was shown to have both nuclear and endoplasmic reticulum localisation in MDA-MB-231 basal breast cancer cells." (PMID 39353922, 2024). "Instead, TMCO1 silencing enhanced apoptosis to navitoclax in MDA-MB-231 cells, and to S63845 in MDA-MB-468 and HCC1806 basal breast cancer cells." (PMID 39353922, 2024). "Given our LC-MS/MS studies showed an enrichment in the TMCO1 interactome in nuclear transport, we evaluated the subcellular localisation of TMCO1 in parental MDA-MB-231 breast cancer cells by performing cell fractionation studies." (PMID 39353922, 2024). "Finally, we also show that TMCO1 silencing can promote apoptosis to navitoclax and S63845, inhibitors of the BCL-2 anti-apoptotic protein family in basal breast cancer cell lines." (PMID 39353922, 2024). "We accessed several publicly available breast cancer patient databases using a web-based gene expression analysis tool (MERAV) and showed that TMCO1 mRNA expression is higher in breast tumours compared to normal breast tissues." (PMID 39353922, 2024).
ocular hypertension (2 papers, 2017 to 2025). Abnormally high intraocular pressure. "TMCO1 contains a common locus with a large effect size for IOP29 and TMCO1 variants predicted conversion from ocular hypertension to POAG in the Ocular Hypertension Treatment Study." (PMID 39982391, 2025).
osteoporosis (2 papers, 2019 to 2025). A condition of reduced bone mass, with decreased cortical thickness and a decrease in the number and size of the trabeculae of cancellous bone (but normal chemical composition), resulting in increased fracture incidence. "Further investigations are needed to explore the potential of TMCO1 as a diagnostic marker or therapeutic target for osteoporosis." (PMID 40867644, 2025). "TMCO1 levels were significantly decreased in bone from both osteoporosis patients and bone-loss mouse models." (PMID 30962442, 2019). "TMCO1 mRNA expression in bone tissues was obviously downregulated in osteoporosis progression, and its levels were positively correlated with the expression of osteogenic marker genes in aged postmenopausal women." (PMID 30962442, 2019). "In this study, we found that TMCO1 levels were significantly decreased in bone specimens from both osteoporosis patients and osteoporotic mice." (PMID 30962442, 2019). "The establishment of TMCO1 as a pivotal player in osteogenesis uncovers a novel potential therapeutic target for ameliorating osteoporosis." (PMID 30962442, 2019). "TMCO1 mRNA and protein levels in osteoporosis patients (T ≤ −2.5) were obviously lower than those in control patients (T > −2.5)." (PMID 30962442, 2019). "Our study establishes TMCO1 as an important regulator in bone formation and provides a new therapeutic target for osteoporosis." (PMID 30962442, 2019). "Regulating TMCO1 gene expression levels or gene knockout may lead to the development of osteoporosis, cancer, and premature ovarian failure (POF)." (PMID 40867644, 2025).
prostate carcinoma (2 papers, 2024). A carcinoma that arises from epithelial cells of the prostate gland. "This study indicated that the overexpression of TMCO1 in prostate cancer tissues was closely related to the invasion and metastasis of prostate cancer." (PMID 39479348, 2024). "Knockdown of TMCO1 expression significantly inhibited the proliferation ability of prostatic cancer cells, Moreover, the knockdown also mitigated the proliferative impact induced by the CALR recombinant protein." (PMID 39479348, 2024). "The experimental outcomes demonstrated that the knockdown of TMCO1 could reverse the effect of CALR in inducing prostate cancer cell metastasis." (PMID 39479348, 2024). "Our study delineates the interplay between TMCO1 and CALR, elucidates their association with the pathological characteristics and prognostic indicators of prostate cancer, and lays a theoretical groundwork for the development of targeted therapeutic interventions." (PMID 39479348, 2024). "Interestingly, TMCO1 gene knockout reduced the invasion and migration ability of prostate cancer cells, concurrent with reduced ER stress, mitochondrial membrane potential, and calcium ion levels." (PMID 39479348, 2024). "In conclusion, TMCO1 plays a key role in the metastasis mechanism of prostate cancer." (PMID 39479348, 2024). "Knockout of TMCO1 can reverse the effect of CALR recombinant protein, elucidating the pivotal roles of TMCO1 and CALR in the regulation of prostate cancer metastasis through modulation of calcium homeostasis." (PMID 39479348, 2024). "In summary, our study delineates the multifaceted roles of TMCO1 and CALR in prostate cancer, underscoring the potential of modulating calcium signaling pathways as a novel therapeutic approach." (PMID 39479348, 2024). "The present study aimed to investigate the relationship between transmembrane and crimp-crimp domain 1 (TMCO1) and calreticulin (CALR) in the pathological characteristics of prostate cancer and the mechanism of action on prostate cancer metastasis." (PMID 39479348, 2024). "The expression level of TMCO1 and CALR were significantly higher in prostate cancer samples than in normal samples." (PMID 39479348, 2024). "This study further demonstrated the regulatory mechanism of TMCO1 and CALR in the metastasis of prostate cancer." (PMID 39479348, 2024). "The inhibition of TMCO1 expression can reverse the effect of CALR induction, providing a theoretical reference for revealing the metastasis mechanism of prostate cancer cells." (PMID 39479348, 2024). "TMCO1 and CALR are overexpressed in prostate cancer and knockdown of TMCO1 significantly inhibited the invasion, migration and cell proliferation." (PMID 39479348, 2024). "Therefore, we propose a hypothesis that TMCO1 and CALR influence ER calcium regulation and mediate prostate cancer cell metastasis." (PMID 39479348, 2024). "Recovery of Ca2+ signals in prostate cancer cells is dependent on SERCA and the activity of SERCA could be altered with TMCO1 silencing as our LC-MS/MS studies identified SERCA2 (ATP2A2) as an interacting partner with TMCO1." (PMID 39353922, 2024).